MT-TW (mitochondrially encoded tRNA-Trp (UGA/G))
Synonyms: trnW; formerly MTTW
Gene: Mitochondrial transfer RNA gene on chromosome MT (5,512 to 5,579, forward strand). Ensembl gene ENSG00000210117.
Gene-disease validity (ClinGen):
ClinGen rates the evidence that MT-TW causes each of these diseases.
mitochondrial disease (mitochondrial): Definitive.
Leigh syndrome (mitochondrial): Limited. A progressive neurological disease defined by specific neuropathological features associating brainstem and basal ganglia lesions.